RBMY1J (RNA binding motif protein Y-linked family 1 member J)
Description:
RNA-binding protein which may be involved in spermatogenesis. Required for sperm development, possibly by participating in pre-mRNA splicing in the testis.
Gene: Protein-coding gene on chromosome Y (22,403,410 to 22,417,881, forward strand). Ensembl gene ENSG00000226941.
Subcellular location: Nucleus
Subcellular location (Human Protein Atlas): Nucleoplasm; Nucleoli
Gene Ontology:
Molecular function: identical protein binding; protein binding; nucleic acid binding; RNA binding
Biological process: mRNA splicing, via spliceosome
Cellular component: spliceosomal complex; nucleus
Homologues: Orthologues: rat Rbmy1j (35% identical), macaque RBMY (35% identical), mouse Rbmyf9 (32% identical), mouse Rbmyf2 (32% identical), mouse Rbmyf3 (32% identical), mouse Rbmy (32% identical), mouse Rbmyf1 (32% identical), mouse Rbmyf5 (32% identical), mouse Rbmyf6 (32% identical), mouse Rbmyf7 (32% identical), mouse Rbmyf8 (32% identical), mouse Rbmyf4 (17% identical). Paralogues in human: RBMY1F (100% identical), RBMY1A1 (99% identical), RBMY1B (99% identical), RBMY1D (99% identical), RBMY1E (99% identical), RBMX (48% identical), RBMXL1 (46% identical), RBMXL2 (38% identical), RBMXL3 (31% identical), CIRBP (17% identical), RBM3 (14% identical), MSI1 (14% identical), and 24 more.
Diseases named in the same sentence as RBMY1J in open-access papers:
RBMY1J is named in the same sentence as 4 diseases in open-access papers, as found by Europe PMC text mining. Sharing a sentence is not in itself a finding about the gene and the disease. The quoted sentences say what the papers report.
cryptorchidism (1 paper, 2019). The failure of one or both testes of a male fetus to descend from the abdomen into the scrotum during the late part of pregnancy. "Our findings implicate Y-chromosomal genes, including USP9Y, UTY, TXLNGY, RBMY1B, RBMY1E, RBMY1J and TSPY4, some of which are known to be important for spermatogenesis, in the curative hormonal treatment of cryptorchidism-induced infertility." (PMID 31171972, 2019).
RBMY1J also shares sentences with these, for which no sentence is quoted: Azoospermia (1 paper); cancer (1); Infertility (1).